ISG15 (ISG15 ubiquitin like modifier)
Diseases named in the same sentence as ISG15 in open-access papers (continued):
Sharing a sentence is not in itself a finding about the gene and the disease.
gastric cancer (12 papers, 2013 to 2025). A primary or metastatic malignant neoplasm involving the stomach. "Indeed, in concordance with its role in replication fork progression, ISG15 is a key determinant of sensitivity to topoisomerase poisons in certain breast, lung and gastric cancer contexts, with higher ISG15 expression being associated with increased sensitivity." (PMID 33203188, 2020). "Subsequent investigations revealed that gastric cancer patients with elevated ISG15 expression demonstrate a markedly decreased overall survival (OS) rate." (PMID 40208307, 2025). "We found that all three elements were significantly positively correlated, i.e., stomach cancer samples with high ISG15 expression were accompanied by high PD-L1 expression and significant M2-TAM infiltration." (PMID 40208307, 2025). "In this study, using multicolor immunofluorescence, we detected the expression levels of ISG15 and a key component of the stomach cancer immune microenvironment, PD-L1, as well as infiltration levels of M2-TAM in human stomach cancer tissues." (PMID 40208307, 2025). "Our analysis indicated that PARP1 expression was negatively correlated with the expression of ISGs (IRF7 and ISG15) in human stomach cancer (n = 407 samples, P < 0.01), which is consistent with our in vitro study observations." (PMID 36624848, 2022). "For HER2+ gastric cancer, the high expression of VIM, IFI44, IFI44L, IFIT2, IFIT3, ISG15, OAS1, or OASL was associated with worse overall survival (P < 0.05)." (PMID 31949544, 2019). "Two studies of tumor tissues from gastric cancer patients found that the level of ISG15 mRNA expression was significantly higher in irinotecan-sensitive tumors than that in the irinotecan-resistant tumors." (PMID 27626310, 2016). "Gene expression levels of APTX, BRCA1 and ERCC1 were significantly lower in irinotecan-sensitive gastric cancer samples than those irinotecan-resistant samples (P < 0.001 for all genes), while ISG15 (P = 0.047) and Topo1 (P = 0.002) were significantly higher." (PMID 23517622, 2013). "Therefore, we postulate that ISG15 plays an instrumental role in the progression of gastric cancer in CC036 mice by involving inflammation and immune dysregulation." (PMID 40208307, 2025). "In our previous research monitoring CC036 mouse stomach cancer development and its immune microenvironment, we proposed that ISG15 might mediate the immune escape microenvironment in immune inflamed stomach cancer that may promote tumor development." (PMID 40208307, 2025). "ISG15 upregulation in esophageal squamous cell carcinoma (ESCC) and gastric cancer is associated with clinical outcomes, suggesting that ISG15 could be used as a prognostic marker." (PMID 36319753, 2022). "The expressions of ISG15 were upregulated in esophageal squamous cancer and gastric cancer." (PMID 35884544, 2022). "In addition, it has been shown that the levels of ISG15 in tumours sensitive to irinotecan in gastric cancer patients are higher than those resistant to irinotecan in gastric cancer patients." (PMID 32641707, 2020). "We interrogated a publically available database to see if we could identify a relationship between expression of UBE2L6 or ISG15 and overall survival in gastric cancer." (PMID 28186990, 2017). "We examined gene expression of APTX, BRCA1, ERCC1, ISG15, Topo1 and methylation of SULF2 in formalin-fixed paraffin-embedded gastric cancer tissues from 175 patients and evaluated the association between gene expression levels or methylation status and in vitro sensitivity to irinotecan." (PMID 23517622, 2013). "Immunohistochemistry and multiplexed immunofluorescence confirmed a strong positive correlation between ISG15, PD-L1, and M2-TAM infiltration in lung and gastric cancer samples." (PMID 40208307, 2025).
gastric cancer (continued). "Conversely, TRIM6 depletion in mouse (MTC) and human (MKN28) gastric cancer cells resulted in a significant increase in the mRNA levels of IFNB1 and its downstream genes CXCL10 and ISG15 (or Ccl5) under HT-DNA treatment, and these effects were abolished by simultaneous cGAS knockout." (PMID 40817248, 2025). "Moreover, employing multiplexed IF staining and IHC, we assessed ISG15 and PD-L1 expression levels, as well as M2-TAM infiltration levels, in cancer tissues from 10 gastric cancer patients from our Nanjing Drum Tower Hospital, and found a significant positive correlation among the three cases." (PMID 40208307, 2025).
lung adenocarcinoma (12 papers, 2020 to 2025). A carcinoma that arises from the lung and is characterized by the presence of malignant glandular epithelial cells. "In vitro and in vivo experiments showed that upregulation of ISG15 inhibited EMT in lung adenocarcinoma." (PMID 40443971, 2025). "ISG15 influenced glycosylated PD-L1 and induced its destruction to increase antitumor immune functions in lung adenocarcinoma." (PMID 38638430, 2024). "Co-immunoprecipitation analyses between DRP1 and ISG15 indicated interaction between the two proteins in A549, lung adenocarcinoma-derived hypotriploid alveolar basal epithelial cells; a band corresponding to mono-ISGylated DRP1 was evident." (PMID 38431611, 2024). "This is accompanied by elevated levels of ISG15 and ISGylation that resemble interferon stimulated lung adenocarcinoma cells (A549) and is likely due to constitutive STAT1 activation." (PMID 37756534, 2023). "Our previous study has demonstrated the effect of ISG15 on lung adenocarcinoma in athymic nude mice." (PMID 37217923, 2023). "In our published article, we have elucidated that ISG15 acts as an independent prognostic marker for lung adenocarcinoma (LUAD) and undergoes ISGylation with ESRP1, reducing ESRP1 degradation." (PMID 37217923, 2023). "A recent study has reported that high expression of ISG15 was correlated with a better prognosis in patients with lung adenocarcinoma." (PMID 34696780, 2021). "Because of our interest in respiratory viruses, including paramyxoviruses, we chose to knockout ISG15 expression in the lung adenocarcinoma cell line A549 by CRISPR/Cas9 genome editing." (PMID 32423918, 2020). "ISG15 increases antitumor immune functions in lung adenocarcinoma." (PMID 38638430, 2024). "Our published articles demonstrate that ISG15 inhibits lung adenocarcinoma progression." (PMID 37217923, 2023). "Lung adenocarcinoma patients with high expression levels of ISG15, MMP1, TRPA1, KRT19, and PLAU (red line) were significantly associated with poor survival rates (log rank P value: 2.3e-07, 0.00034, 0.00037, 0.00057, and 0.023, respectively) as compared to those with low expression (black line)." (PMID 35354498, 2022). "The transwell assay and wound healing assay results also showed that ESRP1 combined with ISG15 could better inhibit the invasion and metastasis of lung adenocarcinoma cells." (PMID 32641707, 2020). "To estimate the survival function of ISG15, MMP1, TRPA1, KRT19, and PLAU, we performed KM plotter analysis generated for groups of lung adenocarcinoma patients based on their expression levels." (PMID 35354498, 2022). "In summary, this article mainly describes the effect of ISG15 in lung adenocarcinoma and the interaction between ESRP1 and ISG15." (PMID 32641707, 2020). "Furthermore, ESRP1 inhibited the invasion and metastasis of lung adenocarcinoma in vivo, and ESRP1 combined with ISG15 synergistically suppressed EMT and lung adenocarcinoma cell invasion." (PMID 38110955, 2023). "However, ISG15, COL14A1 and HBG2 are mainly decreased in lung adenocarcinoma." (PMID 35354498, 2022).
pancreatic ductal adenocarcinoma (12 papers, 2016 to 2025). An infiltrating adenocarcinoma that arises from the epithelial cells of the pancreas. "ISG15 is overexpressed in pancreatic ductal adenocarcinoma, where tumor-associated macrophages secrete ISG15." (PMID 36674743, 2023). "TRIM29 silencing attenuates cancer stem cell-like characteristics of pancreatic ductal adenocarcinomas via regulating ISG15 ubiquitination and degradation." (PMID 37671092, 2023). "Depletion of Bcl-2 associated athanogene 3 (BAG3) impairs ISG15 translation in pancreatic ductal adenocarcinoma (PDAC) cells, suggesting the role of BAG3 in the control of ISG15 expression." (PMID 36319753, 2022). "High levels of free ISG15 were confirmed to be released by M2 macrophages and exert pro-tumor activity in pancreatic ductal adenocarcinoma (PDAC) by regulating PD-L1 expression." (PMID 34579246, 2021). "TAMs secrete ISG15, which contributes to the formation of cancer stem cells of pancreatic ductal adenocarcinoma." (PMID 33424843, 2020). "Evidence supports that the AKT and probably ERK1/2 signaling pathways play a predominant role in ISG15-mediated downstream effects in pancreatic ductal adenocarcinoma CSCs." (PMID 29416698, 2018). "Recombinant ISG15 pronouncedly elevates the self-renewal and sphere-forming capacity in pancreatic ductal adenocarcinoma." (PMID 29416698, 2018). "It has been reported that tumor-associated macrophages (TAMs) secrete ISG15, which enhances cancer stem cell (CSC) phenotypes in pancreatic ductal adenocarcinoma." (PMID 26919245, 2016). "Of note, in pancreatic ductal adenocarcinoma (PDAC), not only does ISG15 extracellular paracrine-signalling play a key role in CSC maintenance, but also the intracellular ISG15 and ISGylation are required for CSC metabolic plasticity and mitophagy." (PMID 35864381, 2022). "Expression of Interferon-stimulated gene 15 (ISG15) is induced by IFN-β and its pathway is highly expressed in various malignancies, including pancreatic ductal adenocarcinoma." (PMID 32967656, 2020). "Parallel to the present results, it was also reported that TAMs secrete ISG15, which promotes CSC phenotypes in pancreatic ductal adenocarcinoma." (PMID 26919245, 2016).
bladder cancer (10 papers, 2006 to 2025). "We performed a gene expression profiling analysis using microarrays and determined that the ISG15 transcript was associated with bladder cancer." (PMID 16641915, 2006). "Taken together, our findings identify ISG15 as a novel component of bladder cancer-associated gene expression." (PMID 16641915, 2006). "This pattern of expression was observed in analyses using two independent microarray platforms, indicating that ISG15 expression is strongly associated with bladder cancer." (PMID 16641915, 2006). "Furthermore, ISG15 expression has been found to be significantly positively associated with advanced stages of bladder cancer." (PMID 36771004, 2023). "Therefore, ISG15 expression in bladder cancer suggests that it is specifically associated with tumour cells." (PMID 18627608, 2008). "Interferons are proinflammatory cytokines that induce high levels of ISG15 expression; therefore, we sought to determine if bladder cancer-associated ISG15 expression may originate from a general response to IFN-mediated inflammation." (PMID 16641915, 2006). "In contrast to the role of ISG15 in breast and urinary bladder cancer, these findings suggest that ISGylation can suppress tumorigenesis." (PMID 27626310, 2016). "The ISG15 gene was significantly upregulated in bladder tumours as compared to normal tissues, and ISG15 protein increased with advancing stage of the bladder cancer." (PMID 16641915, 2006). "The Western blotting analysis revealed consistently increased levels of ISG15 protein in bladder cancer compared to normal samples (P<0.05)." (PMID 16641915, 2006). "Staining of bladder tumour sections and paired normal and tumour samples obtained from the same bladder cancer patient with antibody specific to ISG15 protein revealed a specific expression of ISG15 protein in cancer cells." (PMID 16641915, 2006). "We have performed microarray analysis in combination with Western blotting and immunohistochemical staining to study ISG15 expression in a large population of bladder cancer patients." (PMID 16641915, 2006). "Interestingly, in bladder cancer immunohistochemistry revealed that ISG15 was located predominantly in the nuclei of cancer cells which were associated with an advanced tumour stage." (PMID 18627608, 2008). "Surprisingly, ISG15 overexpression in human bladder cancer has not been found to be associated with a general inflammatory response even though ISG15 was expected to be stimulated by interferon primarily in an inflammatory process." (PMID 18627608, 2008). "Our findings indicate that elevated expression of ISG15 is a novel feature of bladder cancer." (PMID 16641915, 2006). "In agreement with the findings of ISG15 upregulation in diverse tumour cell lines in culture, microarray analyses of human tumour biopsies have revealed enhanced expression of ISG15 in pancreatic adenocarcinoma, endometrial cancer and bladder cancer, when compared with the respective normal tissues." (PMID 18627608, 2008). "Thus, despite its established role as a primary immune response gene, the ISG15 expression in bladder cancer appears to be independent of associated bladder inflammation." (PMID 16641915, 2006). "The innate immune response gene, interferon-stimulated gene 15 kDa (ISG15, GIP2), was highly expressed at all stages of bladder cancer as compared to normal urothelium." (PMID 16641915, 2006). "In addition, ISG15 expression is increased in pancreatic, endometrial, and bladder cancers compared to that in non-cancerous tissues." (PMID 36771004, 2023). "Isg15 was found to be increased in numerous primary human cancers, including endometrial tumors; pancreatic adenocarcinomas; tumors of the breast with Isg15 expression independent of HER2, progesterone, and estrogen receptor status; cancer of the bladder and prostate." (PMID 25071020, 2014).
colorectal cancer (10 papers, 2016 to 2026). A primary or metastatic malignant neoplasm that affects the colon or rectum. "Moreover, a previous study has reported that the down-regulation of ISG15 (type I interferon signaling protein) induced the resistance to cisplatin (one of the platinum drugs) in colorectal cancer cells, which is consistent with our proteomic result." (PMID 33578797, 2021). "ISG15 is upregulated in penta-span transmembrane glycoprotein prominin 1 (PROM1, also known as CD133)-positive colorectal cancer cells compared to PROM1-negative colorectal cancer cells, suggesting the involvement of ISG15 in cancer stemness." (PMID 36319753, 2022). "They identified ISG15 among the 111 transcripts that were upregulated by AIM2, compared with expression levels in AIM2-negative HCT116 cells, and reported a positive correlation between the expression of ISG15 and AIM2 in ten different IFN-γ-treated colorectal cancer cell lines." (PMID 27626310, 2016).
dengue (10 papers, 2011 to 2025). "Regardless, our logistic regressions analyses demonstrates that the expression of ISG15 can predict the course of dengue patients into a more severe outcome." (PMID 26302899, 2015). "ISG15 is a potent antiviral and has been shown to restrict many viruses at various stages of viral life cycle including dengue; therefore, the downregulation of ISG15 may be a viral strategy to evade host immune defense." (PMID 35573775, 2022). "In contrast, interferon-stimulated genes (ISG15 and CXCL10) showed marked upregulation in Dengue patient monocytes, with the strongest expression observed in Dengue with warning sign." (PMID 41012666, 2025). "Next, we analyzed transcriptional changes in HLA-A, HLA-B, ISG15, and CXCL10 across Dengue disease severity." (PMID 41012666, 2025). "This work provides insights into the NDI and vaccine-induced overlapping immune response and suggests molecular markers (e.g., IFIT5, ISG15, and HERC5) for anti-dengue-specific therapies and effective vaccination development." (PMID 38444851, 2024). "Among the ten strongest predictors of dengue severity, IFIT5, ISG15, and HERC5 were the three most important variables." (PMID 38444851, 2024). "When comparing controlled versus hemorrhagic dengue (GSE18090, unpublished data), we found that the individual expression of ISG15, OASL, OAS2 and TNFSF10 can be used to anticipate the complication status of dengue infection into a hemorrhagic outcome." (PMID 26302899, 2015). "Despite the different conditions in vivo, with shifting cell populations and multiple interacting stimuli, 57 of these genes, including canonical ISGs such as ISG15, ISG20, OAS2, ISI27, STAT1 and STAT2, had consistently elevated transcript levels in dengue patients compared to healthy controls." (PMID 23285306, 2012).
breast tumors (9 papers, 2008 to 2025). "In contrast, Isg15 was found to be overexpressed in numerous primary human cancers, including endometrial tumors, pancreatic adenocarcinomas, tumors of the breast, bladder, and prostate." (PMID 25071020, 2014). "The cancer profiling array showed upregulation (fold change ≥ 2) of ISG15 in 33 of 50 primary breast tumours (66%), as well as in one of three metastatic lymph nodes, compared with matched normal breast tissue (two-sided paired t-test: p < 0.001)." (PMID 18627608, 2008). "Interestingly, ISG15 could function as a novel breast tumour marker with prognostic or predictive significance." (PMID 18627608, 2008). "Secreted ISG15 suppressed tumor growth, increased natural killer cell tumor infiltration, and enhanced cell surface MHC class I expression in breast tumors." (PMID 39159817, 2024). "We also compared methylation profiles for Tamoxifen resistant genes, and identified several hypermethylation genes in breast tumors, such as ACTA1, ISG15, PTK6 and SEPHS2." (PMID 23630576, 2013). "Therefore, ISG15 might be a target molecule in the therapy of drug-resistant breast tumours." (PMID 18627608, 2008). "Therefore, the validation set of the additional 646 breast tumours was divided into low ISG15 expressers (IRS = 0 to 3; n = 333) and high ISG15 expressers (IRS = 4 to 12; n = 313)." (PMID 18627608, 2008). "However, using scRNASeq data from breast tumors, we mainly observed an expression of CMKLR1 in a subset of TAM C1QC+ that expressed usual M2 signature, including high expression of CD14 and CD163, whereas CMKLR1 expression was low in a subset of TAM ISG15+ that expressed classical M1 signature." (PMID 37539056, 2023).
ovarian tumor (9 papers, 2013 to 2024). "PL2 belongs to the superfamily of deubiquitinating enzymes (DUΒs) in the ovarian tumor domain, which inhibits the generation of ISG15 and inhibition of ISG15 coupling with cellular proteins." (PMID 35681845, 2022). "Some other viruses, like Dugbe virus (DUGV) and SARS coronavirus, can even hydrolyze ISG15 from target proteins by their ovarian tumor domain- (OTU-) containing proteases or papain-like proteases." (PMID 27867263, 2016). "Recently, exploiting knowledge of the interacting residues to guide mutagenesis studies allowed researchers to engineer the equine arterivirus ovarian tumor domain (vOTU) DUB enzyme with tailor-made specificity to either polyubiquitin or ISG15." (PMID 24854014, 2014). "Moreover, the N-terminal domain of the CCHFV L RdRP contains a protease domain of the OTU (ovarian tumor) family that has the capability to remove both ubiquitin and ISG15 molecules from target proteins." (PMID 32931521, 2020). "Tick-borne nairoviruses (order Bunyavirales) encode an ovarian tumor domain protease (OTU) that suppresses the innate immune response by reversing the post-translational modification of proteins by ubiquitin (Ub) and interferon-stimulated gene product 15 (ISG15)." (PMID 31869347, 2019). "Previous studies have shown that the N-terminal domain of the CCHFV polymerase (L) contains an ovarian tumor-type protease (OTU) domain with the capability to remove both ubiquitin and ISG15 molecules from proteins." (PMID 32931521, 2020). "The ovarian tumour (OTU) domain of the nairovirus L protein has been shown to remove ubiquitin and interferon-stimulated gene 15 protein (ISG15) from host cell proteins, which is expected to have multiple effects on cell signalling pathways." (PMID 23136361, 2013).